CDCA8 (cell division cycle associated 8)
Diseases named in the same sentence as CDCA8 in open-access papers (continued):
Sharing a sentence is not in itself a finding about the gene and the disease.
tumor (continued). "CDCA8 mainly exists in human embryonic stem cells (hESCs) and tumor cells and is rarely expressed in normal tissues." (PMID 36358852, 2022). "Before the end of the experiment, we conducted in vivo fluorescence imaging experiments and weighed the tumor 44 days after injection to verify the inhibitory effect of CDCA8 knockdown on tumor growth." (PMID 35517403, 2022). "The expression of CDCA8 is widely upregulated in various types of tumors and is required for tumor cell growth and progression." (PMID 33801424, 2021). "Upregulated CDCA8 levels were associated with poor TNM stage and a large HCC tumour volume, consistent with our previous bioinformatics analysis results." (PMID 34741389, 2021). "The analysis of CDCA8 expression showed that it was highly expressed in tumor cells and undifferentiated human embryonic stem cells, but no or weakly expressed in normal tissue cells." (PMID 33542211, 2021). "Targeting CDCA8 also effectively suppressed tumor growth in a murine xenograft model, showing consistent molecular alterations in tumors injected with CDCA8siRNA." (PMID 33801424, 2021). "Elevated CDCA8 levels were associated with poor OS, PFS and clinical features, including TNM stages, grades and tumour size." (PMID 34741389, 2021). "Cell division cycle associated 8 (CDCA8) has been well known as a cell cycle regulator and tumor promotor in various malignant tumors." (PMID 33542211, 2021). "After verification of the two selected genes through external databases, we found that: the OS of patients with high expression of CDCA5 and CDCA8 in tumour tissues were significantly decreased from the chip data of GSE4412." (PMID 33449451, 2021). "After 17 days, a remarkable difference (p < 0.001) was apparent in both the weight and size between the control and CDCA8 knockdown groups, showing about a 5-fold delay in tumor growth kinetics." (PMID 33801424, 2021). "The results revealed that CDCA5 and CDCA8 were differentially expressed in tumour and normal tissues of multiple cancer species, showing a tendency of up‐regulation." (PMID 33449451, 2021). "CDCA8 expression is higher in individuals with high stage and grade tumour compared with individuals with low stage and grade tumour (P < 0.05)." (PMID 32377458, 2020). "This study reported that CDCA3, CDCA5, and CDCA8 mRNA expression levels were significantly higher than the control sample in both clinical tumor sample and cancer cell lines, which dramatically reduced patient survival." (PMID 33285689, 2020). "CDCA3, CDCA5, and CDCA8 mRNA expression levels were significantly higher than the control sample in both clinical tumor sample and cancer cell lines." (PMID 29467944, 2018). "Silencing CDCA8 could suppresses tumor growth, proliferation, and stemness of HCC by inactivating AKT/β–Catenin Signaling, and regulating the CDK1/cyclin B1 signaling axis." (PMID 38742112, 2024). "Overexpression of CDCA8 is a reliable predictor of tumor malignancy and a worse clinical prognosis." (PMID 36639822, 2023). "Firstly, we assessed CDCA8 expressions in 15,776 unpaired tumor and normal samples in pan‐cancer." (PMID 36855818, 2023). "Several reports have shown that CDCA8 participates in tumor carcinogenesis." (PMID 35852618, 2023). "Molecular targeted therapy of CDCA8 might be an effective systemic approach to prevent tumor recurrence by eliminating cancer stem cells and cancer cells." (PMID 37433803, 2023). "Previous studies have documented the functional relevance of CDCA8 in tumor cell apoptosis." (PMID 37813876, 2023). "Beyond that, CDCA8 expressed at a high level in MM tissues relative to non-tumor tissues." (PMID 36991473, 2023). "High level of CDCA8 means bad tumor status and poor survival in patients." (PMID 36855818, 2023). "The expression of CDCA8 was significantly higher in tumor tissues, as detected by the IHC assay." (PMID 36358852, 2022).
tumor (continued). "Through subsequent in vivo and in vitro assays, it was found that the knockdown of CDCA8 could also decrease the migration ability of tumor cells, consistent with previous studies and our clinical findings." (PMID 36358852, 2022). "Also, the methylation analysis of CDCAs indicated an association with the tumor immunogenicity, i.e., low-methylation of CDCA1, CDCA2, and CDCA8 dramatically reduced the immune infiltrate levels of T cells and cytotoxic lymphocytes." (PMID 36159969, 2022). "The explanation for this phenomenon is that CDCA8 downregulation blocked the cell cycle in the G2 phase, and the G2-damage checkpoint prevented the cell cycle from entering the M phase, resulting in apoptosis and a low rate of tumor cell proliferation." (PMID 36358852, 2022). "CDCA8 plays a vital role in various tumor-related processes." (PMID 35449575, 2022). "In this study, the database GSE69223 was downloaded by the gene expression omnibus (GEO) database, as well as CDCA8 expression differences in multiple tumor tissues and normal tissues were detected by The Cancer Genome Atlas (TCGA), TIMER, Oncomine, and Ualcan databases." (PMID 35449575, 2022). "However, the concrete functional roles of CDCA8 in tumor initiation, development, and/or progression are still unclear." (PMID 33801424, 2021). "Notably, the inhibition of tumor growth in CDCA8 + shE2F1 group was relatively weaker than that in shE2F1 group." (PMID 33542211, 2021). "Subsequently, we further illustrated weaker fluorescence intensity (P < 0.05), slower tumor growth (P < 0.05), and lighter tumor weight (P < 0.05) in both shE2F1 and CDCA8 + shE2F1 groups in comparison with the respective control group, which was consistent with Ki67 expression in IHC." (PMID 33542211, 2021). "CDCA8 plays essential roles in various tumour‐related processes." (PMID 34741389, 2021). "We next sought to find a molecular explanation of how CDCA8 functions in tumor progression." (PMID 33801424, 2021). "Furthermore, upregulated CDCA8 levels in HCC were significantly correlated with tumour stage, pathological stage and advanced grade." (PMID 34741389, 2021). "In vivo experiments demonstrated that inhibition of CDCA8 inhibited tumour growth." (PMID 34741389, 2021). "Additionally, our study indicated that CDCAs (i.e., CDCA1, CDCA3–6, and CDCA8) have significant hypomethylation levels in tumor tissues of HCC." (PMID 33665158, 2020). "Therefore, CDCA8 plays an important role in the occurrence and development of tumour, and is expected to become a molecular target for tumour therapy and a marker for monitoring patient prognosis." (PMID 32377458, 2020). "Similarly, Pyeon statistics indicate that CDCA8 with a fold change of 1.728 (P = 5.82E-7) and Peng statistics observed a 1.607-fold in tumor samples (P = 1.41E-7)." (PMID 32716971, 2020). "Also, the methylation analysis of CDCAs depicts the strong association with the tumor immunogenicity, i.e., low-methylation of CDCA1, CDCA2, and CDCA8 dramatically reduced the immune infiltrate levels of T cells and cytotoxic lymphocytes." (PMID 33665158, 2020). "CDCA8 (Cell Division Cycle Associated 8) is one of the components of chromosomal passenger complex (CPC) in mitosis and cell division; in fact, CDCA8 was considered as a putative oncogene for it was overexpressed in tumor tissues but had low or undetectable expression in normal tissues." (PMID 31119182, 2019). "CDCA8 and aurora kinase B (AURKB) are overexpressed in tumor cells and selective suppression of the CDCA8-AURKB pathway may be a promising therapeutic strategy in the treatment of cancer." (PMID 26096802, 2015). "In addition, CDCA8-induced tumor survival was completely abrogated by AKT inhibitor MK2206." (PMID 37813876, 2023). "Elevating/silencing CDCA8 could promote/suppress cell functions involved in MM tumor growth." (PMID 36991473, 2023).
tumor (continued). "Additionally, CDCA8 overexpression was positively correlated with AFP levels, increased tumor numbers, vascular invasion, and shorter survival, indicating that CDCA8 is involved in the malignant behavior of HCC and is correlated with worse outcomes for HCC patients." (PMID 36639822, 2023). "In addition, we found that knockdown of CDCA8 promoted the apoptosis of tumor cells." (PMID 36358852, 2022). "Moreover, the higher level of CDCA8 is associated with advanced WHO grade and tumor recurrence." (PMID 33542211, 2021). "Thus, targeting CDCA8 could be a next-line molecular therapy to effectively reduce the tumor burden and block metastasis or recurrence by eliminating both cancer cells and cancer stem cells in the HCC microenvironment." (PMID 33801424, 2021). "Therefore, we postulate that CDCA8 promotes tumour growth through the cell cycle." (PMID 34741389, 2021). "The expression levels of pivotal regulatory genes (CDCA8, AURKA, and PLK1) were significantly higher in tumor samples than in control samples, whereas NR3C2 was significantly downregulated in cancerous tissues." (PMID 41357242, 2025). "CDCA8 knockdown inhibits HCC development and stemness by inactivating oncogenic AKT/β‐catenin signaling and reinstating the ATF3 tumor suppressor." (PMID 39764737, 2025). "For example, CDCA2, CDCA3, and CDCA8 exhibited moderate positive correlations with the immune checkpoint CD276, suggesting that higher CDCA expression might be associated with increased levels of CD276, potentially aiding immune evasion in the tumor microenvironment." (PMID 40114265, 2025). "The results showed an increased expression of ADAMTS5, CDCA8, and LDHA in tumor tissues, suggesting their significant regulatory roles in HCC." (PMID 40647517, 2025). "The qRT−PCR analysis revealed that upregulated expression of CTSC, CDCA8, and G6PD, whereas downregulated expression of CXCL9 in HCC compared with adjacent tumor tissue and normal liver cell lines." (PMID 38742112, 2024). "Based on our investigation, CDCA8 was strongly upregulated in HCC, and it accelerated tumor cell proliferation and infiltration." (PMID 36855818, 2023). "The results showed that CDCA8 and SPP2 methylation levels were decreased in tumor tissues with worse clinical stages." (PMID 38057871, 2023). "From 1895 metastasis-related genes, they found that the expression of SLC2A1, CDCA8, ATG10, and HOXD9 was higher in HCC tumor tissue whereas the expression of TPM1 was lower." (PMID 37974228, 2023). "Many researchers have identified CDCA8 as a novel oncogene, which predicts a poor prognosis in HCC as well as promotes tumor proliferation via MEK/ERK, AKT/β-Catenin, and CDK1/cyclin B1 signaling." (PMID 37854038, 2023). "The results showed that CDCA8 was highly expressed and RDH16 was lowly expressed in HCC tumor tissues." (PMID 38057871, 2023). "We observed that compared with shCtrl group, mice injected with CDCA8 knockdown CAL-62 cells had smaller tumor volume, slower growth rate and therefore smaller tumor size." (PMID 35517403, 2022). "For instance, CDCA8 knockdown inhibits HCC development and stemness by restoring the ATF3 tumor suppressor and inactivating AKT/β-catenin signaling." (PMID 36302799, 2022). "In this study, at the molecular level, we found that silencing of CDCA8 suppresses the growth and stemness of HCC tumor cells through the restoration of tumor suppressor ATF3 and inactivation of the AKT/β–catenin signaling axis." (PMID 33801424, 2021). "We found that targeting CDCA8 inhibits HCC growth and stemness via the restoration of the ATF tumor suppressor and inactivation of the AKT/β–catenin signaling axis." (PMID 33801424, 2021).
tumor (continued). "Consistent with transcriptional profiling of the knockdown of CDCA8 expression, the protein levels of the ATF3 and GADD34 tumor suppressors were restored in the same condition." (PMID 33801424, 2021). "Upregulated CDCA8 levels were significantly positively correlated with poor TNM stage (p = 0.028) and tumour size (p = 0.005)." (PMID 34741389, 2021). "The expression levels of SLC2A1, CDCA8, ATG10 and HOXD9 are higher in tumor samples and lower in normal tissue samples." (PMID 34116652, 2021). "After comparing the expression level of the tumor tissue and the paracancer tissue in each case, we found that the expression levels of CDCA2, CDCA3, CDCA5 and CDCA8 were overexpressed in tumor tissues in each patient." (PMID 32913466, 2020). "In this research, we further assessed the differential expression of five hub genes (TPX2, KIF2C, CDCA8, BUB1B, and CCNA2) in various clinical stages, and the results showed that their expression was significantly increased in advanced tumour stages." (PMID 31285741, 2019). "In the case of AURKB, phosphorylation of CDCA8 by AURKB can play a role in promoting cell growth, survival and xenograft tumor growth." (PMID 26842935, 2016). "Mechanistically, CDCA8 and TROAP converge on pathways of mitotic fidelity and chromosomal segregation, processes that may promote chromosomal instability, tumor evolution, and therapeutic resistance." (PMID 41008819, 2025). "CDCA8 is a putative oncogene that is overexpressed in numerous cancer types and is essential for tumor invasion and metastasis; moreover, CDCA8 is widely expressed in embryonic tissues but is absent or expressed at low levels in normal adult cells." (PMID 39335162, 2024). "Although not statistically significant, it should be observed that CDCA8 promoted tumor growth in vivo." (PMID 33542211, 2021). "Moreover, by analyzing gene expression in GSE6764 cohort, we found that the expression levels of PDSS1, CDCA8 and SLC7A11 were significantly higher in tumor tissue than those in liver nodules." (PMID 32887635, 2020). "The expression score of CDCA8 in tumour tissues was significantly higher than that in normal tissues." (PMID 32377458, 2020). "Notably, CDCA3, CDCA4, CDCA5, and CDCA8 exhibited elevated expression trends in the radiation-resistant cohorts, consistent with the TCGA-READ database findings showing preferential CDCA family overexpression in tumor specimens." (PMID 40565588, 2025). "Our analyses of TCGA and GTex tumor data and matched normal samples from TCGA and GTex datasets using the Gene Expression Profiling Interactive Analysis (GEPIA) tool showed that KIFC1, AURKB, BIRC5, and CDCA8 are all significantly overexpressed in many different cancer types." (PMID 39335162, 2024). "We first compared the expression differences of MAPT, WDR62, PLK1, CDCA8 and TOP2A in normal hepatocyte tissues and HCC tissues by TCGA database, and the results showed that the expression levels of MAPT, WDR62, PLK1, CDCA8 and TOP2A were significantly higher in tumour cells than in normal tissues." (PMID 39072983, 2024). "The results showed that patients with high CDCA8 expression tend to having higher T stage (OR = 1.698 for T3 & T4 vs. T1 & T2), higher PS (OR = 1.750 for Stage III & IV vs. Stage I & II), higher HG (OR = 2.616 for G3 & G4 vs. G1 & G2) and poorer TS (OR = 1.838 for with tumor vs. tumor free)." (PMID 36855818, 2023). "Furthermore, it was discovered that CDCA8 promoted the proliferation and invasion of PDAC via transcriptional regulation of CD44, a transmembrane receptor participating in the progression and metastasis of tumor cells." (PMID 36358852, 2022). "The activation of the tumor suppressive ATF3/GADD34 functional pathway and the inactivation of the AKT/β–catenin pathway was observed in general in all the experimental HCC environments of parental cell culture, isolated CSCs, and xenograft-tumors with CDCA8 depletion." (PMID 33801424, 2021).
tumor (continued). "CDCA8 expression has also been shown to be involved in several signatures, such as hypoxia-related signature, metastasis-related mRNAs, and glycolysis-related genes, which could also predict HCC diagnosis and prognosis, and may reflect different tumor immune or metabolic microenvironments." (PMID 36639822, 2023). "Compared to either untreated or non-targeting controls, cells lacking HRNR or CDCA8 showed significantly reduced proliferation; by contrast, the loss of KRT14 did not affect proliferation, suggesting that it was not required for tumour cell viability or growth." (PMID 31443478, 2019). "While the initiating cells in recurrent tumors were mainly related to the cell cycle such as MKI67, CKS2, ANLN, CDC20, CDCA8, CENPF, inflammatory signals no longer drive anti-tumor immunity." (PMID 41601649, 2026).